CA1 (carbonic anhydrase 1)
Diseases named in the same sentence as CA1 in open-access papers (continued):
Sharing a sentence is not in itself a finding about the gene and the disease.
prostatitis (1 paper, 2021). An infectious or non-infectious inflammatory process affecting the prostate gland. "An experiment recently found that the Zn-binding proteins superoxide dismutase 3 (SOD3) and carbonic anhydrase 1 (CA1) were present in high quantities in prostatitis when compared to control." (PMID 34070833, 2021).
thalassemia (1 paper, 2021). An inherited blood disorder characterized by a decreased synthesis of one of the polypeptide chains that form hemoglobin. "The high levels of carbonic anhydrase transcripts (CA1) in our dataset led us to exclude the possibility of a reversion to a fetal form of erythropoiesis in MKD, similarly to thalassemia patients." (PMID 33525735, 2021).
tongue tumor (1 paper, 2018). "Among 24 candidates, 8 proteins including Myosin light chain family members (MYLPF, MYL4 and MYL2), creatinine kinase, serotransferrin, heat shock protein A8, carbonic anhydrase 1 and Glyceraldehyde-3-phosphate dehydrogenase were significantly downregulated in tongue tumor tissues." (PMID 29371635, 2018).
Valvular Heart Diseases (1 paper, 2017). "Using the same experimental approach, Gao and colleagues identified the over-representation of Carbonic anhydrase 1 in human patients of Valvular Heart Diseases." (PMID 28173805, 2017).
viral infection (1 paper, 2007). "It is noteworthy that T cells derived from healthy HIV-1-seronegative individuals did not initiate proliferation in the presence of cA1 peptide (data not shown), suggesting that the cA1 peptide recognition might have been processed after the viral infection." (PMID 18043730, 2007).
tumor (37 papers, 2015 to 2026). "The decrease in carbonic anhydrase 1 (encoded by Ca1) and delta-aminolevulinic acid dehydratase (encoded by Alad) induced in the spleen by tumor progression concurred with our histological observations on the red pulp, as these enzymes are specific to erythroid cells." (PMID 34445271, 2021). "TMIP 0 (high CA-1, “immune hot/active”) was defined by higher B_Non-regulatory, T_CD8_Cytotoxic states and a lower T_CD8_Mixed state, which displayed an active immune response underlined by the functional impact of its corresponding cell states on tumor immunity." (PMID 38082384, 2023). "Thus, we continued to genotype this tag SNP to determine whether the CA1 gene had possible associations with the various types of tumours that were examined in the current study." (PMID 26459317, 2015). "In this study, several proteins with proteoforms were also identified in the tumor margin and center, including lamin, L-plastin, aldehyde dehydrogenase 2, and carbonic anhydrase 1 for ADC and cyclophilin B for SCC." (PMID 35512017, 2022). "Two proteoforms of carbonic anhydrase 1 (CA1) showed changes in the opposite direction: spot 1828 increased in abundance in the tumor center, while spot 1961 increased in the margin." (PMID 35512017, 2022). "When the tumour cells were grown in the presence of the anti‐CA I positive sera of the patients with spontaneous tumour regression, the expression of the CA1 gene has been increased." (PMID 28782909, 2018). "Additionally, LPS treatment altered the ACSL5, ENPP6, and CA1 expression in the intestine and tumor enteroids." (PMID 35884586, 2022). "In this study, we identified several metabolic enzymes with higher abundance due to knockdown of CA1 mRNA that may play an important role in tumour progression: TPI, protein‐glutamine‐gamma‐glutamyltransferase 2, peroxidasin homolog and pyruvate kinase (PKM)." (PMID 30916466, 2019). "In vivo studies have also confirmed the role of CA1, miR-125b-5p, miR-107, and NSE in tumor progression and chemoresistance as demonstrated by increased tumor sizes, migration, angiogenesis, and reduced sensitivity to chemotherapy." (PMID 39767730, 2024). "The activities of CA1, ANXA10, and MUC1 were increased in LPS treated IBD enteroids compared to the LPS treated tumor enteroids, while the activities of BAAT, ACSL5, and ENPP6 were decreased." (PMID 35884586, 2022). "In the sera of cancer patients with spontaneous tumor regression after high dose therapy and autologous stem cell transplantation, a high titer of human anti-CA1 autoantibodies (anti-CA I Abs) was discovered." (PMID 31963697, 2020). "By comparing with the normal group, we found that apolipoprotein B (APOB) and carbonic anhydrase 1 (CA1) were significantly up-regulated, whereas angiopoietin like 5 (ANGPTL5) and shisa family member 7 (SHISA7) were down-regulated in the tumor samples." (PMID 33050883, 2020). "Simultaneously, in the presence of sera with anti-CA I Abs, the expression of the CA1 gene mRNA was upregulated among all tested tumor cell lines." (PMID 31963697, 2020). "The in vivo studies confirmed the pathogenic effects of DLBCL-derived Evs, as seen in the promotion of tumor growth and invasiveness, as well as the role of specific EV cargoes, such as CA1, miR-125b-5p, miR-107, and NSE, in tumor progression and chemoresistance." (PMID 39767730, 2024). "Although panomics revealed low RNA and protein expression of CA1, CLCA1, MATN2, AHCYL2, and FCGBP in malignant tissues compared to healthy colon mucosa, no differentially expressed RNA or protein targets were detected between tumour and metastatic tissues." (PMID 36691026, 2023). "Similar to curcumin (Cur), CA-1 has the characteristics of inducing tumor death through chemotherapy to enhance tumor immunogenicity, and effectively recruit CD4+T helper cells (Th) and CD8+ cytotoxic T lymphocytes (CTL) for the enhancement of anti-tumor immune responses." (PMID 37153576, 2023).
cancer (32 papers, 1983 to 2025). A tumor composed of atypical neoplastic, often pleomorphic cells that invade other tissues. "The most common alterations in cancer for the CA1 gene are amplifications, as high as 40%, in neuroendocrine prostate cancer, prostate adenocarcinomas and metastatic cancers." (PMID 29495652, 2018). "We postulated that C4-2 genes were likely to be found in advanced cancers; the strongest candidate was carbonic anhydrase 1 (CA1), expression of its transcript was restricted to metastases with a possible increase in bone." (PMID 16042785, 2005). "Moreover, 19 upregulated proteins (including keratin 1 protein and rheumatoid factor RF-IP20, ratio>1.5) and 8 downregulated proteins (including carbonic anhydrase 1, ratio<0.667) were identified from malignant ascites samples." (PMID 30345303, 2018). "This is noteworthy that abundances of C-reactive protein and angiogenin generally upregulated in cancers samples further increased in metastatic samples, while abundances of carbonic anhydrase 1 generally downregulated in cancer samples further decreased in metastatic samples." (PMID 26376850, 2015). "Among cancer and precancerous lesions glycoproteins, we further highlight seven glycoproteins found in high-grade dysplasia as well as cancer (IGHG1, CPA2, MYH2, AZU1, PRTN3, CA1, SMPDL3B), holding potential for non-invasive detection of aggressive traits." (PMID 38612533, 2024). "We conclude that the Ca1 antibody is not sufficiently specific for the carcinoma to be of value in the diagnosis of malignant and premalignant lesions of the oral mucosa." (PMID 6354238, 1983). "C1-2 cells lacked reported cancer cell functional alterations, suggesting that they are enriched in normal epithelial cells, and C1 cells expressed markers of mature colonocytes (GUCA2B, SLC26A3 and CA1)." (PMID 36209225, 2022).
infection (10 papers, 2013 to 2025). The state of being infected such as from the introduction of a foreign agent such as serum, vaccine, antigenic substance or organism. "Heme/hemoglobin metabolism was enriched in groups 1, 2, and 4, with four common genes (ALAS2, AHSP, HBD, and CA1) that are associated with the immune response to infection." (PMID 41839673, 2025). "Mutations in Ca1 decreased significantly after Period 2, suggesting that the amino acid residues in Ca1 seem to become well-adapted for infection of humans." (PMID 24147093, 2013). "Two proteins, carbonic anhydrase I (CA1) and Charcot-Leyden crystal galectin (CLC) are common interacting targets of TRP120 and TRP47, suggesting their importance during infection." (PMID 28553621, 2017). "Two selected ECM-MP proteins, carbonic anhydrase 1 (CA-I) and S100A8, were further verified on a larger number of samples and their abundance was proven to be increased within plasma MP specifically released during the infection." (PMID 27917875, 2016).
CA1 also shares sentences with these, for which no sentence is quoted: colitis (6 papers); glaucoma (5); lung cancer (5); autoimmune disease (4); colorectal tumors (3); diabetic retinopathy (3); hepatocellular carcinoma (3); non-small cell lung carcinoma (3); Obesity (3); Retinal hemorrhage (3); abdominal aortic aneurysm (2); autoimmune pancreatitis (2); bladder cancer (2); diabetic macular edema (2); glioma (2); malignant melanoma (2); meningioma (2); metabolic syndrome (2); pancreatitis (2); Sjogren syndrome (2); systemic lupus erythematosus (2); acute myeloid leukemia (1); altitude sickness (1); Alzheimer disease (1); arteriopathy (1); bipolar II disorder (1); breast fibroadenoma (1); cataract (1); Cerebral ischemia (1); cerebral malaria (1).
A further 48 diseases each share a sentence with CA1 in 1 paper.